FAM66C (family with sequence similarity 66 member C)
Gene: Long non-coding RNA gene on chromosome 12 (8,180,204 to 8,226,278, forward strand). Ensembl gene ENSG00000226711.
Diseases named in the same sentence as FAM66C in open-access papers:
FAM66C is named in the same sentence as 14 diseases in open-access papers, as found by Europe PMC text mining. Sharing a sentence is not in itself a finding about the gene and the disease. The quoted sentences say what the papers report.
glioma (5 papers, 2022 to 2023). A benign or malignant brain and spinal cord tumor that arises from glial cells (astrocytes, oligodendrocytes, ependymal cells). "Herein, nine ferroptosis-related lncRNAs (AC062021.1, FAM66C, MIR497HG, TMEM72-AS1, AC010729.2, FAM225B, HOXA-AS2, LINC00662, and LINC00665) were identified to construct a risk model in patients with glioma." (PMID 35174152, 2022). "FAM66C acts as a tumour suppressor in glioma by targeting miRNA/LATS1 signalling." (PMID 37980632, 2023). "Long non-coding RNA FAM66C regulates glioma growth via the miRNA/LATS1 signaling pathway." (PMID 35935338, 2022). "The expression levels of AC062021.1, SNHG6, LINC00507, FAM66C, DGCR10, and LINC00641 were significantly lower in glioma tissues than in normal brain tissues (P < .05) and gradually increased with the degree of malignancy." (PMID 37145002, 2023).
prostate carcinoma (4 papers, 2021 to 2024). A carcinoma that arises from epithelial cells of the prostate gland. "For instance, FAM66C was found to inhibit the proliferation of pancreatic cancer cells, while paradoxically promoting the proliferation of prostate cancer cells." (PMID 39143529, 2024). "In contrast, FAM66C is elevated in prostate cancer, and high FAM66C expression promotes tumour growth by activating EGFR-ERK signalling through inhibition of the proteasome pathway." (PMID 37980632, 2023). "It has been proven that the lncRNA FAM66C activates the EGFR-ERK pathway to promote cell proliferation in prostate cancer." (PMID 34490250, 2021).
intrahepatic cholangiocarcinoma (3 papers, 2023 to 2025). A carcinoma that arises from the intrahepatic bile duct epithelium in any site of the intrahepatic biliary tree. "FAM66C overexpression increased glycolytic activity in human intrahepatic cholangiocarcinoma cell lines." (PMID 38347610, 2024). "FAM66C drives intrahepatic cholangiocarcinoma progression and glycolysis by sponging miR-23b-3p and thus upregulating KCND2 expression." (PMID 37980632, 2023). "FAM66C was also significantly increased in intrahepatic cholangiocarcinoma." (PMID 37980632, 2023). "Some scholars have also found that lncRNA FAM66C regulates downstream target genes to drive intrahepatic cholangiocarcinoma progression and glycolysis activity through sponge action of miR-23b-3p, suggesting that FAM66C may be a potential target for the treatment of ICC." (PMID 41466006, 2025).
gastric cancer (1 paper, 2023). A primary or metastatic malignant neoplasm involving the stomach. "In addition, FAM66C has been incorporated into prognostic models for melanoma, gastric cancer and glioblastoma (GBM)." (PMID 37980632, 2023).
lung carcinoma (1 paper, 2023). "Additionally, we found that FAM66C is highly expressed in lung cancer patients for the first time, which is associated with poor prognosis." (PMID 37980632, 2023). "FAM66C plays an oncogene role in NSCLC development by promoting lung cancer cells’ proliferation and migration capacity." (PMID 37980632, 2023). "We also found that the expression of FAM66C was upregulated in lung cancer cell lines compared to normal lung bronchial epithelial cells." (PMID 37980632, 2023). "Additionally, the FAM66C interference effect on migratory ability in lung cancer cells was verified by wound-healing assay and migration assay." (PMID 37980632, 2023). "However, functions of FAM66C in lung cancer remain elucidated." (PMID 37980632, 2023).
viral meningitis (1 paper, 2024). Inflammation of the membranes surrounding the brain and spinal cord due to a viral infection. "In viral meningitis specific co-expression networks, a total of 9 significantly upregulated lncRNAs (AC243830.1, AC092111.1, CEROX1, AC246817.2, FAM66C, LINC01535, LINC02848, CHKB-DT, and C18orf15) were identified." (PMID 38347610, 2024).
cancer (5 papers, 2019 to 2023). A tumor composed of atypical neoplastic, often pleomorphic cells that invade other tissues. "The results indicated that the mRNA level of FAM66C was significantly increased in the cancer tissues of NSCLC patients." (PMID 37980632, 2023). "The risk signature of our study included 8 lncRNAs (CRNDE, LINC00844, FAM66C, TUBA3FP, SNHG8, HAR1A, LINC00641, and MYCNOS), and previous evidence has suggested that these lncRNAs are closely linked to the occurrence and development of cancer." (PMID 35832170, 2022). "For group 1, seven of the thirteen novel-loci-related coding or noncoding genes, namely F11/F11-AS1, PFKFB3, PRMT8, FAM66C, NAV2/NAV2-AS1, FRMD4A, and KIAA0232, have been demonstrated to be correlated with the development of HCC or other cancers in many studies." (PMID 38003606, 2023).
tumor (3 papers, 2022 to 2024). "Conversely, AP000253.1 and FAM66C were highly expressed in the high-risk subgroup, indicating their role as tumor risk factors." (PMID 39143529, 2024). "The results of cellular experiment validation revealed that FAM66C was closely associated with tumour proliferation and migration." (PMID 37980632, 2023). "Consistent with these conclusions, we found that the expression of FAM66C in high-risk patients was significantly lower than that in low-risk patients, suggesting that FAM66C is more likely to play the role of a tumor suppressor gene in tumor cells and prevent tumor progression." (PMID 35769464, 2022). "High expression of FAM66C activates EGFR-ERK signaling by inhibition of the proteasome pathway promoting tumor growth." (PMID 39143529, 2024). "FAM66C knockdown significantly inhibited the proliferation and migration ability of the tumour cells." (PMID 37980632, 2023). "FAM66C is a long noncoding RNA that has been found to regulate glycolysis and inhibit the proliferation and migration of tumor cells." (PMID 35769464, 2022). "The results above suggested that FAM66C may play an oncogene role in the process of NSCLC development, and FAM66C knockdown significantly influenced the prefiltration and migration ability of the tumour cells." (PMID 37980632, 2023). "Thus, we tried to explore whether the FAM66C affects the proliferation of tumour cells, the results of apoptosis assay showed an increased percentage of apoptosis of cells after knockdown of FAM66C, including early and late apoptosis." (PMID 37980632, 2023).
FAM66C also shares sentences with these, for which no sentence is quoted: cholangiocarcinoma (2 papers); pancreatic cancer (2); asthma (1); breast carcinoma (1); glioblastoma (1); melanoma (1).